ENSG00000278920 (novel transcript, sense overlapping SMTN)
Gene: Long non-coding RNA gene on chromosome 22 (31,051,630 to 31,068,327, forward strand). Ensembl gene ENSG00000278920.
Gene Ontology:
Biological process: SRP-dependent cotranslational protein targeting to membrane, signal sequence recognition
Cellular component: signal recognition particle, endoplasmic reticulum targeting